MCM6 (minichromosome maintenance complex component 6)
Diseases named in the same sentence as MCM6 in open-access papers (continued):
Sharing a sentence is not in itself a finding about the gene and the disease.
neuroblastoma (3 papers, 2013 to 2023). Neuroblastoma (NB) is the most common solid, extracranial childhood tumor. "Publicly available datasets were used to explore the influence of the differential expression of MCM6 on neuroblastoma tumor stage, risk and prognosis." (PMID 34233647, 2021). "Through multiple datasets mining, we found that high expression of MCM6 was positively correlated with elevated tumor stage, high risk and poor prognosis in neuroblastoma." (PMID 34233647, 2021). "Analysis of clinical significance showed that high expression of MCM6 is related to the progression and high risk of neuroblastoma." (PMID 34233647, 2021). "In summary, our data show that high expression of MCM6 significantly associates with poor prognosis of neuroblastoma." (PMID 34233647, 2021). "In neuroblastoma, in a pre-clinical cell model, proliferation, migration, and invasion were significantly inhibited after MCM6 was interfered by siRNA." (PMID 36672484, 2023). "We found that the neuroblastoma cell cycle was blocked in G1/S after the inhibition of MCM6 expression." (PMID 34233647, 2021). "In the Kocak, SEQC and Oberthuer datasets, neuroblastoma patients with high MCM6 expression all showed poorer OS and EFS than low MCM6 expression cohorts." (PMID 34233647, 2021). "In neuroblastoma, studies have reported that the MCM complex is directly regulated by the transcription factor MYCN, but there are very few studies on the tumor characteristics and prognosis of MCM6 and neuroblastoma." (PMID 34233647, 2021). "In order to comprehend the function of MCM6 in neuroblastoma cells, we designed three siRNAs (siRNA1, siRNA2 and siRNA3) to silence the expression of MCM6." (PMID 34233647, 2021). "At the cellular level, neuroblastoma cell proliferation, migration and invasion were significantly inhibited after MCM6 was interfered by siRNA." (PMID 34233647, 2021). "In in vitro experiments, we found that MCM6 promotes the migration and invasion of neuroblastoma cells, which were consistent with those reports." (PMID 34233647, 2021). "Here we studied the expression of MCM6 in neuroblastoma and its influence on tumor characteristics and prognosis." (PMID 34233647, 2021). "In this study, we provided evidence that MCM6 is a potential novel therapeutic target for neuroblastoma patients." (PMID 34233647, 2021). "After interfering expression of MCM6, the neuroblastoma cells from G1 to S phase are blocked, which means that the process of DNA replication is disturbed." (PMID 34233647, 2021). "MCM6 is considered to be the driving force of G1/S cell cycle progression, and it is also a prognostic marker and a potential novel therapeutic target in neuroblastoma." (PMID 34233647, 2021). "We further explored the possible molecular mechanism of MCM6 affecting the phenotype of neuroblastoma cells by mutual verification of RNA-seq and western blotting, and flow cytometry to inquire about its potential specific roles in the cell cycle." (PMID 34233647, 2021). "At the same time, wound healing and Matrigel-coated (for invasion) or-uncoated (for migration) Transwell analysis showed that MCM6 knockout effectively inhibited the invasion and metastasis of neuroblastoma." (PMID 34233647, 2021). "In order to explore the role of MCM6 in the ability of neuroblastoma tumorigenesis in vivo, we established the shMCM6 SK-N-BE stable cell line (LV-shMCM6) to study its biological functions in a mouse model." (PMID 34233647, 2021). "Flow cytometric analysis revealed that neuroblastoma cells were blocked in G1/S phase after MCM6 interference." (PMID 34233647, 2021). "Through in vitro experiments, we found that MCM6 silencing can significantly inhibit neuroblastoma cell proliferation, migration and invasion." (PMID 34233647, 2021). "To identify potential targets regulated by MCM6 in neuroblastoma, we performed RNA-seq in SK-N-BE cell line." (PMID 34233647, 2021).
neuroblastoma (continued). "With this approach we identified four genes that are highly over expressed in high-risk neuroblastoma (CHAF1A, RRM2, MCM3, and MCM6) whose expression strongly correlates with poor outcomes." (PMID 24348903, 2013). "In vitro experiments show that MCM6 is expressed at a higher level in neuroblastoma cell lines." (PMID 34233647, 2021). "Next we evaluated the clinical relevance of MCM6 in pediatric neuroblastoma." (PMID 34233647, 2021). "We boldly hypothesize that in neuroblastoma, MCM6 may promote the proliferation and poor prognosis of neuroblastoma by regulating the cell cycle process of neuroblastoma." (PMID 34233647, 2021). "We started our research by examining the expression of MCM6 mRNA in 31 neuroblastoma specimens." (PMID 34233647, 2021). "We examined the effect of MCM6 expression on the growth of neuroblastoma cells in vitro." (PMID 34233647, 2021). "Effective intervention of MCM6 is likely to become an effective new treatment for neuroblastoma." (PMID 34233647, 2021). "This study proved the importance of the expression of MCM6 in neuroblastoma, and MCM6 may be a new prognostic indicator and a potential novel therapeutic target of neuroblastoma patients." (PMID 34233647, 2021). "All these results indicate that MCM6 may play an important role in the development of neuroblastoma." (PMID 34233647, 2021). "Therefore, we boldly speculate that the activation of Wnt/β-catenin signaling pathway is an important mechanism for MCM6 to induce neuroblastoma metastasis." (PMID 34233647, 2021). "In addition, we analyzed MCM6 expression in neuroblastoma of high-risk group and low-risk group in the SEQC dataset, and found that the expression of MCM6 in neuroblastoma in the high-risk group was significantly higher than that in the low-risk group (p < 0.001)." (PMID 34233647, 2021). "MCM6 acts as a tumor promoter by activating CDK4-Cyclin D1 signaling, and subsequently regulates cell cycle progression in G1/S phase in neuroblastoma." (PMID 34233647, 2021). "Therefore, we believe that MCM6 may be a promising neuroblastoma biomarker." (PMID 34233647, 2021).
ovarian carcinoma (3 papers, 2015 to 2021). A malignant neoplasm originating from the surface ovarian epithelium. "Analyses of eight unique datasets were performed for MCM2, MCM4, and MCM6 in ovarian cancer, and three were significant." (PMID 34178669, 2021). "Microliposome maintenance (MCM) 2, MCM3, MCM4, MCM5, MCM6, and MCM7 are DNA replication regulators and are involved in the progression of multiple cancer types, but their role in ovarian cancer is still unclear." (PMID 34178669, 2021).
triple-negative breast carcinoma (3 papers, 2021 to 2022). An invasive breast carcinoma which is negative for expression of estrogen receptor (ER), progesterone receptor (PR), and human epidermal growth factor receptor 2 (HER2). "Overexpression of MCM2, MCM3, MCM4, and MCM6 is associated with luminal B, HER2+, and triple-negative breast cancers." (PMID 35401937, 2022).
anemia (2 papers, 2018 to 2019). A reduction in the number of red blood cells, the amount of hemoglobin, and/or the volume of packed red blood cells. "We examined global transcriptome alterations following depletion of DNA replication checkpoint genes (Atr, Mcm4, Mcm5, and Mcm6), the Fanconi anemia gene (Fanca), mRNA processing genes (Snrpal and Snrpd3), and CMT genes (Sh3tc2 and Cmt4b2)." (PMID 31390555, 2019).
Cirrhosis (2 papers, 2018 to 2026). A chronic disorder of the liver in which liver tissue becomes scarred and is partially replaced by regenerative nodules and fibrotic tissue resulting in loss of liver function. "More importantly, serum MCM6 levels in HCC patients were significantly higher than those in cirrhosis and healthy controls (P < 0.0001), and allowed distinguishing early recurrence with high accuracy (AUC = 0.773)." (PMID 29357919, 2018). "Firstly, when discerning HCC patients from cirrhosis and healthy controls, serum MCM6 had significant sensitivity (P < 0.0001)." (PMID 29357919, 2018).
colon cancer (2 papers, 2020). "Among these proteins, AE1 is thought to be present in gastric and colon cancer cells; while PCNA, MCM6, α/β/γ-actin and α/β-tubulin, among others, have been observed in a lymphoblastoid cell line." (PMID 32204550, 2020).
COVID-19 (2 papers, 2023 to 2024). A disease caused by infection with severe acute respiratory syndrome coronavirus 2. "In our study, seven genes (BUB1, PRC1, KIFC1, RRM2, CDKN3, CCNB2, and MCM6) were involved in the interaction between COVID-19 and silicosis." (PMID 37278873, 2023). "Finally, submodule analysis showed that PRC1, KIFC1, BUB1, MCM6, CCNB2, CDKN3, and RRM2, which were hub-shared genes of silicosis and COVID-19, possessed the highest mCODE scores." (PMID 37278873, 2023).
developmental delay (2 papers, 2023 to 2025). "We additionally traced three unrelated individuals with de novo MCM6 variants in the oligonucleotide binding (OB)-fold domain, presenting with variable (neuro)developmental features including autism spectrum disorder, developmental delay, and epilepsy." (PMID 37198333, 2023). "We observed a recognizable clinical phenotype, including primary microcephaly, short stature, endocrine features and developmental delay, in individuals with a MCM6 variant affecting the zinc binding residue." (PMID 37198333, 2023). "The three additional individuals (individual 3, 4 and 5) with putative pathogenic variants in MCM6 presented with more variable (neuro)developmental phenotypes including developmental delay/regression, autism spectrum disorders, epilepsy and hypertonia." (PMID 37198333, 2023). "Recent genomic analyses have identified de novo missense MCM6 variants in individuals with ASD, developmental delay, and epilepsy." (PMID 41009596, 2025).
head and neck cancer (2 papers, 2025). A primary or metastatic malignant neoplasm affecting the head and neck. "MCM6 showed similar correlations, except in HPV+ head and neck cancer, while MCM4 was positively correlated with C1GALT1 across all cancer types." (PMID 40548474, 2025).
lymph node metastasis (2 papers, 2019 to 2022). "Univariate analysis revealed that depth of invasion, lymph node metastasis, distant metastasis, and CDK5RAP3 and MCM6 expression were associated with patients' overall survival." (PMID 31528213, 2019).
lymphoma (2 papers, 2005 to 2014). A malignant (clonal) proliferation of B- lymphocytes or T- lymphocytes which involves the lymph nodes, bone marrow and/or extranodal sites. "The percentage of MCM6 expressing lymphoma cells ranged from 12.0 to 95.6%, with a mean of 61.0%, and was significantly higher than the percentage of Ki-67-positive cells (P<0.0001)." (PMID 16189522, 2005). "Since we have developed an antibody that accurately identifies MCM6 in paraffin-embedded tissues, an expression pattern that was tested in normal peripheral blood mononuclear cells, we chose this antibody to determine MCM protein expression in this lymphoma." (PMID 16189522, 2005).
rectal adenocarcinoma (2 papers, 2020 to 2025). "The MCM6 was 2.053- and 2.142-fold higher in colon and rectal adenocarcinoma samples respectively compared with the normal tissues." (PMID 32597491, 2020).
sarcoma (2 papers, 2021). A usually aggressive malignant neoplasm of the soft tissue or bone. "Overexpression of MCM6 in sarcoma was also found in both datasets." (PMID 34239894, 2021). "We found that except for MCM1, all other MCM factors had higher expression levels in sarcoma than in normal tissues (p < 0.05 for MCM2, MCM4, MCM5, MCM6 and MCM7)." (PMID 34239894, 2021).
anaplastic oligodendroglioma (1 paper, 2021). A WHO grade III oligodendroglioma with focal or diffuse malignant morphologic features (prominent nuclear pleomorphism, mitoses, and increased cellularity). "Two previous studies indicated that MCM6 was involved in immune progression dysregulation and might be a target for immunotherapy for systemic lupus erythematosus and anaplastic oligodendroglioma." (PMID 34178669, 2021).
autism (1 paper, 2025). Persistent deficits in social interaction and communication and interaction as well as a markedly restricted repertoire of activity and interest as well as repetitive patterns of behavior. "The Simons Foundation Autism Research Initiative (SFARI) also classifies MCM6 as a strong candidate ASD gene (Category 2) due to recurring damaging mutations in ASD cohorts." (PMID 41009596, 2025).
autism spectrum disorder (1 paper, 2023). A spectrum of developmental disorders that includes autism, and Asperger syndrome. "The last affected individual (individual 5) presented with a de novo variant in MCM6 (NM_005915.5 (MCM6): c.445C > T, p.(Pro149Ser)) and was previously reported in a large study cohort on autism spectrum disorders." (PMID 37198333, 2023). "However, despite extensive genetic testing, no variants in candidate genes that could potentially explain her autism spectrum disorder were identified, other than the variant in MCM6." (PMID 37198333, 2023).
brain cancer (1 paper, 2022). A primary or metastatic malignant neoplasm affecting the brain. "In agreement with our finding, MCM6 has been reported to exert oncogenic functions in liver, breast, and brain cancers." (PMID 36185598, 2022).
brain tumor (1 paper, 2020). "To further investigate the relations between the cell decrease and proliferation ability, we looked at the association of the CKAP2L versus the commonly used proliferation biomarkers in the TCGA dataset, including MKI67 and MCM6 expression, which have been used in other brain tumor studies." (PMID 33375517, 2020). "To further support the proposal that the decrease of cell number was due to the decline of proliferation ability, we looked at the association of the CKAP2L versus two common proliferation biomarkers in the TCGA and CGGA datasets, including MKI67 and MCM6, often used in brain tumor studies." (PMID 33375517, 2020).
breast invasive carcinoma (1 paper, 2025). "In this study, we found MCM6 is upregulated in breast invasive carcinoma (BRCA) and is associated with poorer overall survival by regulating the DNA damage repair mechanisms." (PMID 39477811, 2025).
colorectal neoplasm (1 paper, 2019). A benign or malignant neoplasm that affects the colon or rectum. "The group of patients that were diagnosed with colorectal neoplasm and MCM6 expression levels below 85%, a significantly poor OS (p = 0.008) and PFS (p < 0.001) were monitored in the univariate analysis." (PMID 31072339, 2019).
diffuse large B-cell lymphoma (1 paper, 2021). "MCM6 has also been used to identify cancer cell proliferation and may be a useful prognostic biomarker in diffuse large B-cell lymphoma." (PMID 34490114, 2021).
esophageal cancer (1 paper, 2022). A primary or metastatic malignant neoplasm involving the esophagus. "The research found MCM6 was an oncogene and could promote esophageal cancer cells proliferation." (PMID 35069893, 2022).
Ewing sarcoma (1 paper, 2025). A small round cell tumor that lacks morphologic, immunohistochemical, and electron microscopic evidence of neuroectodermal differentiation. "Further supporting a critical role for the MCM2–7 and the pre-RC in Ewing sarcoma tumors, the Dbf4-dependent Cdc7 kinase (DDK), which initiates replisome assembly by phosphorylating the N-terminal tails of Mcm2, Mcm4, and Mcm6, was recently identified as a target in Ewing sarcoma tumors." (PMID 40478628, 2025).
fibrosarcoma (1 paper, 2021). A malignant mesenchymal fibroblastic neoplasm affecting the soft tissue and bone. "In Detwiller Sarcoma’s datasets, MCM6 was overexpressed in leiomyosarcoma (fold change = 5.847), fibrosarcoma (fold change = 5.500), malignant fibrous histiocytoma (fold change = 4.896) and synovial sarcoma (fold change = 4.175)." (PMID 34239894, 2021).
gastric tumor (1 paper, 2019). "In patients, immunohistochemistry and immunofluorescence show that the protein levels of CDK5RAP3 were markedly decreased in most gastric tumor tissues compared with adjacent nontumor tissues, and the expression levels of MCM6 in the nucleus showed the opposite trend." (PMID 31528213, 2019).
hepatitis B infection (1 paper, 2018). "Statistical analysis indicated that high MCM6 expression was associated with hepatitis B infection, liver cirrhosis, multiple tumor nodules, high serum AFP and early recurrence." (PMID 29357919, 2018).
hyperuricemia (1 paper, 2023). An abnormally high level of uric acid. "Furthermore, MCM6/LCT might be a potential therapeutic target for treating hyperuricemia." (PMID 37063923, 2023). "MCM6 could be activated by both DHA supplements in the human body and hyperuricemia status in mice." (PMID 37063923, 2023).
infertile (1 paper, 2022). "Additionally, aberrant overexpression of MCM2 and MCM6 may cause abnormal epithelial proliferation and nonreceptive endometrium in infertile women with endometriosis." (PMID 35232969, 2022). "However, aberrant overexpression of MCM2 and MCM6 may cause abnormal epithelial proliferation and nonreceptive endometrium in infertile women with endometriosis." (PMID 35232969, 2022).
invasive ductal carcinoma (1 paper, 2022). "MCM6 can differentiate between histologic grades of invasive ductal carcinoma (P < 0.001) with a meaningful correlation with mitotic figures, which is also stronger than that of Ki-67." (PMID 35125121, 2022).
liver cirrhosis (1 paper, 2018). "Clinical significance analysis indicated that MCM6 was associated with tumor number, liver cirrhosis and early recurrence." (PMID 29357919, 2018).
mammary adenocarcinoma (1 paper, 2015). "This phenylalanine aligns in sequence with a phenylalanine of Mcm4 whose mutation, Mcm4(Chaos3), severely disrupts Mcm4:Mcm6 association and has been associated mammary adenocarcinoma." (PMID 26365238, 2015).
mastitis (1 paper, 2022). Inflammation of breast tissue during lactation or postpartum due to an obstructed duct or infection. "In this study, the increased gene expression of ORC1, ORC2, ORC4, MCM3, MCM5, and MCM6 in the neutrophils of cows with high SCCs indicated that the cell cycle may be activated in neutrophils in high mastitis risk cows during the transition period." (PMID 35572521, 2022).
medulloblastoma (1 paper, 2017). A malignant, invasive embryonal neoplasm arising from the cerebellum. "Interestingly, here we found that Gmnn levels in human medulloblastomas did not correlate with tumor subtype, histology, or other criteria, but did correlate with elevation of cell cycle related genes, including pre-RC proteins (MCM6, ORC1, and ORC6)." (PMID 29234490, 2017).
metastatic disease (1 paper, 2025). "This study aims to investigate the potential predictive effect of known histopathological features in PCC/PGL, alongside SDHB, S100, Ki-67 proliferation index, and the expression of MAML3 and MCM6 in predicting metastatic disease." (PMID 40445576, 2025). "This study aims to explore the potential predictive effects of MAML3 and MCM6 expression, in addition to known histopathological features, SDHB, S100, and the Ki-67 proliferation index, in forecasting metastatic disease in PCC and PGL." (PMID 40445576, 2025).
pancreatitis (1 paper, 2015). Inflammation of the pancreas. "The DEGs, including Cdc6, Mcm6, Msh6 and Wdr1 are closely associated with the regulation of caerulein-induced pancreatitis." (PMID 25975747, 2015). "Therefore, increased expression of Mcm6 may be due to the loss of Mist1 function, and thus enhances pancreatitis via increased proliferation." (PMID 25975747, 2015). "In conclusion, high expression of Cdc6 and Mcm6 may lead to increased cell proliferation and pancreatitis." (PMID 25975747, 2015). "In addition, specific TFs, including minichromosome maintenance complex component 7 (Mcm7); lymphoid-specific helicase (Hells); and minichromosome maintenance complex component 6 (Mcm6), that function in the unwinding of DNA were identified to participate in Mist1KO pancreatitis." (PMID 25975747, 2015).